RN7SKP228 (RN7SK pseudogene 228)
Gene: Miscellaneous RNA gene on chromosome 7 (12,876,684 to 12,876,946, forward strand). Ensembl gene ENSG00000222974.
Homologues: Orthologues: chimpanzee 7SK (99% identical). Paralogues in human: RN7SKP180 (78% identical), RN7SKP45 (76% identical), RN7SKP255 (76% identical), 7SK (75% identical), RN7SKP204 (75% identical), RN7SKP9 (75% identical), RN7SKP171 (75% identical), RN7SKP176 (75% identical), RN7SKP189 (75% identical), RN7SKP37 (75% identical), RN7SKP113 (74% identical), RN7SKP243 (74% identical), and 284 more.